MMP3 (matrix metallopeptidase 3)
Diseases named in the same sentence as MMP3 in open-access papers (continued):
Sharing a sentence is not in itself a finding about the gene and the disease.
osteoarthritis (continued). "We found that the anti-CD13 blocking antibody AB108310 for murine chondrocytes and SJ1D1 for osteoarthritis human chondrocytes, inhibited the chondrocyte response to recombinant 14-3-3ε by decreasing the expression and release of MMP-3 and MMP-13." (PMID 26208633, 2015). "Accordingly, MMPs secreted from chondrocytes and activated synoviocytes are involved in cartilage destruction, and MMP-3 and IL-6 are known markers of rheumatoid arthritis and osteoarthritis." (PMID 25884474, 2015). "Serial synovial tissue sections from all RA patients, 13 osteoarthritis, and 10 orthopedic arthropathies patients were stained with hematoxylin and eosin and immunohistochemically for MMP-3, CD3, CD20, CD38, CD68, and CD15." (PMID 25147433, 2014). "Most importantly, the expressions of key proinflammatory genes such as Il6, Vcam1, Ccl7, Mmp3, Mmp13, enhanced in rheumatoid arthritis and osteoarthritis, were reduced." (PMID 24199619, 2013). "We intentionally included key proinflammatory mediators, genes of matrix metalloproteinase (Mmp3, Mmp13), which are known to degrade collagen in cartilage and thereby enhance rheumatoid arthritis and osteoarthritis progression." (PMID 24199619, 2013). "Our results demonstrate that the signaling through TLR-4 is a proinflammatory mechanism in osteoarthritis that drives the upregulation of MMP-3, IL-1β, and TNF-α gene expression, leading to cartilage degradation and inflammation." (PMID 23118784, 2012). "This suggests that MMP-3 siRNA has the potential to be a useful preventive and therapeutic agent for osteoarthritis." (PMID 20034400, 2009). "MMP-3, also known as stromelysin-1, catalyzes the degradation of several substrates, including cartilage proteoglycan, collagen types II, IV, IX, and XI, laminin, and fibronectin, and is closely related to osteoarthritis severity." (PMID 40429909, 2025). "In addition, inhibition of the Wnt/GSK-3β/NF-κB signaling axis can directly suppress MMP3 promoter activity, thereby ameliorating the progression of osteoarthritis." (PMID 40918434, 2025). "Furthermore, a substantial decrease was observed in the mRNA expression of inducible nitric oxide synthase, cyclooxygenase-2, 5-lipoxygenase, IL-6, TNF-α and MMP-3 and -13, thereby indicating promising therapeutic implications for osteoarthritis." (PMID 38542192, 2024). "Chronic circadian rhythm disruption could lead to osteoarthritis-like pathological changes in rat knees, with increased expression of MMP3, MMP13, and ADAMTS4 in knee cartilage and decreased expression of BMAL1." (PMID 39010104, 2024). "Previous studies have reported that Atractylodes lancea inhibited osteoarthritis by suppressing the expression and activity of MMP3, and Atractylodes lancea inhibited migration and invasion of hepatocellular carcinoma cells by decreasing the expression level of MMP9." (PMID 39177661, 2024). "MMP-3 levels in the blood could be used as a prospective disease indicator and a biomarker for osteoarthritis of the knee." (PMID 37259405, 2023). "However, numerous preclinical studies investigated serum level of MMP-3 in osteoarthritis after MSCs transplantation in animal models." (PMID 37316949, 2023). "A previous study demonstrated that dexamethasone had a chondroprotective effect, that is, it ameliorated arthritic pain and protected cartilage from damage in a rabbit osteoarthritis model via suppressing several pro-inflammatory gene markers, including il-1b, il-8, il-6, tnf-α, mmp-3, and mmp-13." (PMID 36429168, 2022). "Caspase‐3 plays an important role in facilitating cell apoptosis, whereas MMP‐3 and inflammatory cytokines promote further deterioration of osteoarthritis and cartilage damage by degrading extracellular matrix components and are highly expressed in inflammatory tissues." (PMID 33304230, 2020). "The induction of MMP-3 has been related to miR-149 and miR-454 expression in osteoarthritis." (PMID 32189997, 2020).
osteoarthritis (continued). "Other than that, several studies showed increased MMP-3 in osteoarthritis." (PMID 32189997, 2020). "HIF-2α downstream degradation factors, such as MMP-3,13 and ADAMTs-4,5, played essential roles in the degradation of cartilage aggrecan and had been recognized as one of the most primary targets for therapeutic intervention in osteoarthritis." (PMID 32083119, 2019). "In addition, the relative expression levels of MMP3 detected in synovial cells of osteoarthritis patients and normal donors by western blot and qRT‐PCR were consistent with microarray results." (PMID 30560591, 2019). "Importantly, we verified that high expression of MMP3 would promote cell proliferation and inhibit cell apoptosis, increasing osteoarthritis inflammation in the end." (PMID 30560591, 2019). "This study not only provided a treatment strategy for osteoarthritis but also proved that MMP3 may be a new biomarker for judging the prognosis of osteoarthritis." (PMID 30560591, 2019). "Curcumin could reduce cell viability, inhibit cell proliferation, increase cell apoptosis, and eventually alleviate inflammation of osteoarthritis by inhibiting the expression of MMP3." (PMID 30560591, 2019). "In our study, MMP3 was found to be overexpressed in osteoarthritis synovial cells." (PMID 30560591, 2019). "Curcumin could downregulate the expression of MMP3, promote apoptosis, and inhibit cell proliferation, as well as ultimately alleviate osteoarthritis inflammatory response." (PMID 30560591, 2019). "By inhibiting MMP3 in osteoarthritis, inflammation and cartilage degradation should decrease." (PMID 31052496, 2019). "MMP-1 and MMP-3 are overexpressed in the synoviocytes and chondrocytes of osteoarthritis patients." (PMID 28445942, 2017). "MMP-1 and MMP-3 are the main MMPs produced by fibroblasts and macrophage-like cells in the synovium, with significantly higher levels found in the synovial fluid of patients with RA compared to patients with osteoarthritis." (PMID 27564851, 2016). "Synovial fluid MMP-3 in patients with RA and patients with osteoarthritis (OA) was also analyzed." (PMID 27209430, 2016). "Given that MMP-1, MMP-3 and MMP-13 play pivotal roles in the cartilage matrix breakdown associated with both RA and osteoarthritis, the inhibitory effects of acacetin on MMPs indicates a potential role for acacetin in preventing cartilage degradation associated with RA." (PMID 25856795, 2015). "We investigated the anti-inflammatory and immunomodulatory effect of simvastatin on articular cartilage via the inhibition of matrix metalloproteinase-3 (MMP-3), a matrix-degrading enzyme, in a mechanically induced experimental osteoarthritis (OA) animal model." (PMID 21863259, 2011). "MMP-3 is expressed in a variety of cells other than gingival fibroblasts, including monocytes, endothelial cells, chondrocytes, and synovial cells, and is known to destroy connective tissue in chronic inflammatory diseases, such as periodontitis, rheumatoid arthritis, and osteoarthritis." (PMID 37110385, 2023). "Down-regulates MMP3 and TNF-a genes; reduces the loss of cell matrix of rat chondrocytes; maintains cell activity; down-regulates the expression of genes related to cell inflammation; reduces inflammation; and exerts a certain therapeutic effect on osteoarthritis in vitro." (PMID 35566359, 2022). "NLRP3 inflammasome has been implicated in osteoarthritis pathological progression through secreting proinflammatory cytokines including IL-1β and tumor necrosis factor-alpha (TNF-a), producing cartilage degrading enzymes like MMP3 and aggravating synovial membrane inflammation." (PMID 35935815, 2022). "MMP-3 is associated with the susceptibility of KBD, and the imbalance expression of MMPs / TIMPs leading to cartilage degradation may play an important role in cartilage degradation and osteoarthritis formation in OA and KBD." (PMID 34980041, 2022).
osteoarthritis (continued). "Similarly, our study revealed that curcumin could decrease the expression of MMP3 on osteoarthritis synovial cells, inhibit proliferation, and promote apoptosis." (PMID 30560591, 2019). "In addition, studies have shown that LDW pills could effectively inhibit the expression of IL-beta, MMP-1 and MMP-3, thus protecting and repairing the articular cartilage which had significant therapeutic effects on Osteoarthritis." (PMID 29212201, 2017). "Thus RNAi targeting on MMP-3 may become an effective therapeutic method for osteoarthritis in the future." (PMID 20034400, 2009). "Preceding studies demonstrated that MMP3 and MMP13 increased in chondrocytes to increase osteoarthritis progression by a ferroptosis promoter like ferric ammonium citrate." (PMID 40622464, 2025). "HA injections have shown the ability to slow osteoarthritis progression by reducing glycosaminoglycan release and pro-inflammatory molecules, such as MMP-13, MMP-3, and IL-1β." (PMID 40943818, 2025). "In a mouse model of posttraumatic osteoarthritis, curcumin has been found to slow the progression of osteoarthritis and relieve its symptoms by reducing the levels of MMP-1, MMP-3, MMP-13, ADAMTS5, IL-1β, and TNF-α." (PMID 37938371, 2024). "In our MIA-induced osteoarthritis animal model, BSRE administration diminished the production and content of MMP-3 and -13 in the serum and suppressed the expression of MMP-2, -3, and -13 mRNA in the synovium." (PMID 38542192, 2024). "High expression levels of MMP3, MMP13, and ADAMT4 in articular cartilage of osteoarthritis signify excessive extracellular matrix degradation, thereby accelerating the course of osteoarthritis." (PMID 39840130, 2024). "Compared to synovial fluid from osteoarthritis patients, RA subjects have higher concentrations of MMP-1, MMP-2, MMP-3, MMP-8, and MMP-9, especially MMP-3 which reaches extremely elevated levels." (PMID 38338785, 2024). "Piperine has an anti-inflammatory effect and can inhibit the expression levels of inflammatory factors (iNOS, COX-2) and degenerative factors (MMP3, MMP13) in IL-1β-stimulated osteoarthritic chondrocytes, thereby treating osteoarthritis." (PMID 37525208, 2023). "Rats with osteoarthritis had greater serum MDA and knee joint MMP-3, NF-κB, and TGβ protein levels and decreased in treated groups with UCII and NA (p < 0.05)." (PMID 34282229, 2021). "Osteoarthritis research society international (OARSI) score in cartilage was markedly increased, along with increased MMP‐3, MMP‐13, ADAMTS‐5, ICAM‐1, ERK and p‐ERK expression." (PMID 33939302, 2021). "The percentage of methylated CpG sites of these MMP genes in clonal chondrocytes from osteoarthritis patients versus controls were: 80% versus 96% for MMP13, 19% versus 53% for MMP9, and 43% versus 70% for MMP3." (PMID 33920915, 2021). "In in vitro and in vivo models of osteoarthritis, shikonin inhibited inflammatory responses by reversing the elevated expression of MMP1, MMP3, and MMP13." (PMID 34812264, 2021). "TNF-α’s activity blockade through soluble PEGylated TNFR1 was shown to decrease the production of MMP-1, MMP-3 and MMP-13 in femoral condylar cartilage cells cultured from osteoarthritis patients." (PMID 34201546, 2021). "Specifically, key clinical parameter (MMP-3 and TIMP-1) were obtained from blood probes of German shepherd dogs with early osteoarthritis symptoms fed with collagen hydrolysates." (PMID 34677442, 2021). "The mRNA expression of catabolic factors MMP-3, MMP-7, and MMP-13 was significantly decreased in rat in the FJH-KO100 and FJH-KO150 groups compared with that in rats with MIA induced osteoarthritis (p < 0.05)." (PMID 33233504, 2020). "Level of leptin in synovial fluid of osteoarthritis patients undergoing total knee replacement surgery positively correlated with the levels of MMP-1 and MMP-3." (PMID 33396484, 2020). "MMP-3, MMP-9, and MMP-13 levels increased in animals induced with osteoarthritis, but the TIMP-2 level was shown to decline." (PMID 32189997, 2020).
osteoarthritis (continued). "We analyzed MMP expression to assess the anti-osteoarthritis effects of LI73014F2 and showed that a 50 mg/kg dose of the compound significantly reduced MMP-2, MMP-3, and MMP-13 levels." (PMID 33238379, 2020). "Such a pathological mechanism has been proposed for MMP-3 and MMP-13 in degenerative joint disease in the elderly." (PMID 32116759, 2020). "In vitro and in vivo studies demonstrated that CJM reduced the IL‐1β‐, IL‐6, IL‐17‐ and TNF‐α‐induced up‐regulation of MMP3, MMP13, ADAMTS4, ADAMTS5 and COX‐2 and blocked osteoarthritis development in a destabilization of the medial meniscus mouse model." (PMID 31148341, 2019). "MMP-3 and MMP-13 have been found in increased levels at the sites of cartilage erosion in cases of rheumatoid arthritis and osteoarthritis." (PMID 30691120, 2019). "Previous report has shown that increased MMP-1, MMP-3, MMP-9, MMP-12, and MMP-13, VEGF-A, and COL10A1, triggered by hypoxia-inducible factor (HIF)-2, play a vital role during osteoarthritis development." (PMID 31766662, 2019). "In vivo study confirmed that DAS protected the cartilage in the development of osteoarthritis by inhibiting the expression of MMP-1, MMP-3, MMP-13, and IL-1β as well as enhancing the production of collagen II." (PMID 29370858, 2018). "For instance, it has been shown to inhibit the expression of MMP-3, MMP-13, iNOS, and COX-2 on human osteoarthritis (OA) in vivo, thus, making diosgenin a suitable agent for OA therapy." (PMID 29370858, 2018). "Specific MMPs, such as MMP-1 (collagenase-1), MMP-3 (stromelysin-1), and MMP-13 (collagenase-3), degrade cartilage proteoglycans and type II collagen, leading to osteoarthritis." (PMID 29348767, 2017). "The study set out to determine the levels of metalloproteinases MMP-1, MMP-3 and MMP-8, as well as tissue inhibitor TIMP-1 in patients with osteoarthritis, following the administration of anti-rheumatic agents." (PMID 32185271, 2017). "Compared with the control group, the mRNA and protein levels of MMP1, MMP3, and MMP13 increased significantly in IL-1β-stimulated human osteoarthritis chondrocytes." (PMID 29179489, 2017). "Among the MMPs, MMP-3 and MMP-13 are known to play crucial role in osteoarthritis cartilage destruction." (PMID 26208633, 2015). "Serum and synovial levels of MMP1, MMP3 and MMP13 are increased in rheumatoid arthritis and osteoarthritis." (PMID 24739658, 2014). "The present study investigated the effects of an aqueous extract of Eucommia on the articular cartilage (by Mankin’s grade) and the levels of matrix metalloproteinase-1 (MMP-1), MMP-3 and MMP-13 in the serum and synovial fluid in a rat model of osteoarthritis." (PMID 24137247, 2013). "Both the total and phosphorylated forms of SYK are expressed in increased levels in RA synovial tissues compared with osteoarthritis, and SYK inhibition reduced the expression of IL-6 and MMP-3." (PMID 23249408, 2012). "This is in agreement with an animal study that reported an increase in markers of osteoarthritis in dogs with acetabular dysplasia (including IL-1β, IL-6, tumor necrosis factor (TNF)-alpha, and matrix metalloproteinase (MMP)-3) in comparison to normal dogs." (PMID 20367415, 2010). "C3GC can also significantly reduce levels of MMP-3 and TNF-α in dogs with osteoarthritis." (PMID 40431555, 2025). "GLP-1 RAs such as liraglutide, exenatide, lixisenatide, dulaglutide, and geniposide share common chondroprotective mechanisms in osteoarthritis, including suppression of NF-κB (reducing IL-6, TNF-α, and COX-2), inhibition of matrix-degrading enzymes (MMP-3/13, ADAMTS-4/5), and attenuation OS." (PMID 41158135, 2025). "Isoliensinine demonstrates anti-inflammatory and chondroprotective effects in osteoarthritis by reducing extracellular matrix degradation, NLRP3 activation, and Matrix metalloproteinase 3 (MMP-3) expression while inhibiting MAPK/NF-κB signaling and chondrocyte pyroptosis." (PMID 41154606, 2025).
osteoarthritis (continued). "Sleep deprivation could activate the p-ERK pathway in rat mandibular condylar chondrocytes, increases the expression of matrix-degrading enzymes MMP1, MMP3, and MMP13, and leads to osteoarthritis-like lesions in the temporomandibular joint." (PMID 39010104, 2024). "Future research will focus on analyzing the protein expression of MMP-2, MMP-3, MMP-9, and MMP-13 to more fully elucidate the molecular mechanisms by which BSRE impacts osteoarthritis progression, providing valuable insights for developing more effective therapeutic strategies." (PMID 38542192, 2024). "Several genetic and non-genetic factors can increase the expression of MMP3 in patients with osteoarthritis (OA)." (PMID 37000824, 2023). "Because cartilage erosion is a common pathological alteration in OA, targeting some key metalloproteinases such as MMP-3, ADAMTS-5 besides their inhibitor TIMP-3 by natural products, could be an effective strategy to protect against osteoarthritis." (PMID 37259405, 2023). "Additionally, the expression of MMP-3、TIMP-1 in different layers of the articular cartilage was analyzed by immunohistochemistry for 22 KBD patients, 15 osteoarthritis (OA) patients and 21 controls." (PMID 34980041, 2022). "Human osteoarthritis chondrocytes can be inhibited by senegenin by inhibiting PI3K/AKT/NF-κB signaling pathway, inhibiting the expression of MMP-1, MMP-3, and MMP-13 induced by IL-1β, and the production of NO and PGE2 was reduced in human osteoarthritis chondrocytes." (PMID 35924058, 2022). "MMP3 and MMP9 are upregulated in chondrocytes in osteoarthritis." (PMID 35164658, 2022). "Furthermore, biochemical parameters are also altered as found in our analysis of the blood-probes with respect to osteoarthritis markers (e.g., TIMP-1, MMP-3)." (PMID 34677442, 2021). "Similarly, leptin alone and by co-stimulation with IL-1ß enhanced the production of MMP-1, MMP-3, and MMP-13 in knee cartilage from patients with osteoarthritis." (PMID 33396484, 2020). "In human osteoarthritis synovium, paquinimod treatment blocked MMP1 and MMP3 secretion." (PMID 33005006, 2020). "A recent systematic review assessing COMP, CTX-11, and MMP-3 in knee and hip osteoarthritis patients found that COMP and urinary CTX-11 can distinguish osteoarthritis patients from healthy, with COMP effectively able to predict osteoarthritis progression." (PMID 31650307, 2019). "We determined the interleukin 6 (IL-6), IL-6 receptor α (IL-6Rα), gp130, receptor activator of nuclear factor κB ligand (RANKL), matrix metalloproteinase 3 (MMP3), TIMP metallopeptidase inhibitor 1 (TIMP1), and Bcl-2 levels in RA and osteoarthritis (OA) serum and synovial fluid." (PMID 29755657, 2018). "Serum MMP-3 is elevated in diseases that involve joint synovitis, including RA, reactive arthritis, psoriatic arthritis, and crystal arthritis, but not in osteoarthritis (OA) or systemic inflammatory conditions such as sepsis." (PMID 27209430, 2016). "HIF-2α is involved in a pathway that promotes osteoarthritis degradation and regulates the expression of genes related to chondrocyte hypertrophy and differentiation, such as COL10A1 and RUNX2, and the expression of genes related to ECM degradation, such as MMP9, MMP13, MMP3, ADAMTS." (PMID 36503684, 2022). "In addition, the factors used to treat osteoarthritis include TNF-α, IL-6, MMP3 and MMP13." (PMID 35566359, 2022). "Importantly, our study revealed that FA suppressed MMP‐1, MMP‐3, and MMP‐13 production stimulated by IL‐1β in vitro, suggesting that FA may be effective for restoring ECM composition and structure to halt osteoarthritis progression." (PMID 34078001, 2021). "The purpose of this study was to evaluate matrix metalloproteinases (MMP) -2 and MMP-3 in serum, and keratinocyte-derived chemoattractant (KC), interleukin 8 (IL-8) and monocyte chemoattractant 1 (MCP-1) in synovial fluid (SF) as stifle osteoarthritis (OA) biomarkers in dogs." (PMID 33211763, 2020).